EXO1 (exonuclease 1)
Diseases named in the same sentence as EXO1 in open-access papers (continued):
Sharing a sentence is not in itself a finding about the gene and the disease.
HIV-1 infection (2 papers, 2018 to 2021). The type species of lentivirus and the etiologic agent of acquired immunodeficiency syndrome (AIDS). "Importantly, ectopic expression of the RNAi-resistant Exo1 variant restored restriction of HIV-1 infection in the endogenous Exo1-depleted CEM.SS_iExo1r cells (left and right, Dox+)." (PMID 30352932, 2018). "One could speculate, based on the available data, that Exo1 restricts an early step(s) in HIV-1 infection." (PMID 30352932, 2018). "HIV-1 infection depletes Exo1 levels in human CD4+ T cells in a Vpr-dependent manner." (PMID 30352932, 2018). "We identify exonuclease 1 as a member of a new class of HIV-1 restriction factors in T cells and propose that certain modes of DNA “repair” inhibit HIV-1 infection." (PMID 30352932, 2018). "The failure of RNAi-mediated Exo1 depletion to restore replication of vpr-deficient HIV-1(vpr.Q8*) to levels seen for HIV-1(vpr.wt) is evidence that Exo1 is not the only Vpr-antagonized protein inhibiting HIV-1 infection in CEM.SS T cells." (PMID 30352932, 2018).
Infertility (2 papers, 2015 to 2024). "To determine if the loss of EXO1 modified the phenotypes of Nbs1ΔB, we crossed Nbs1+/ΔB Exo1+/− double heterozygous animals to generate double mutants, as homozygosity of either allele leads to subfertility or infertility respectively." (PMID 26160886, 2015). "Inactivation of EXO1 in mice resulted in infertility, ovarian dysgenesis, and POI, which was attributed to a dynamic loss of chromosomes chiasmata during the first meiotic prophase, indicating its pivotal role in oogenesis." (PMID 39595984, 2024).
laryngeal carcinoma (2 papers, 2018 to 2019). Carcinoma that arises from the laryngeal epithelium. "The EXO1 rs1047840 GA genotype was associated with complete recovery in patients with laryngeal cancer treated using cisplatin and RT." (PMID 31035658, 2019).
liver cirrhosis (2 papers, 2016 to 2020). "High expression of EXO1 was significantly associated with the presence of liver cirrhosis (p=0.005)." (PMID 32626539, 2020). "Here, we show that EXO1 is significantly upregulated in HCC tumor tissues and that high EXO1 expression is significantly correlated with liver cirrhosis." (PMID 32626539, 2020).
medulloblastoma (2 papers, 2020 to 2023). A malignant, invasive embryonal neoplasm arising from the cerebellum. "For example, almost all the genes in the mismatch repair pathway have elevated gene expression levels in medulloblastoma, except EXO1, RPA3 and POLD4." (PMID 36918656, 2023).
prostate adenocarcinoma (2 papers, 2021). "Compared with normal samples, EXO1, RMI2, and RAD51 were significantly overexpressed in most cancer types including BRCA, while RMI2 was significantly lower expressed in PARD (Prostate adenocarcinoma)." (PMID 34408776, 2021).
adenoma (1 paper, 2025). A neoplasm arising from the epithelium. "Time series analysis using the likelihood ratios showed differences in expression of genes including Fos, Lama3, Aldh1a3, Col7a1 and Doks associated with increased induction by t = 12 h, whereas E2f8, Exo1, Clspn, Kif14 and Kif12 all were decreased in Smad4+/+ adenomas." (PMID 40348815, 2025).
Aicardi-Goutieres syndrome (1 paper, 2021). Aicardi-Goutieres syndrome (AGS) is an inherited, subacute encephalopathy characterized by the association of basal ganglia calcification, leukodystrophy and cerebrospinal fluid (CSF) lymphocytosis. "Diseases associated with EXO1 include Werner’s syndrome and Aicardi-Goutieres syndrome." (PMID 33912448, 2021).
bladder cancer (1 paper, 2021). "In a recent article on the regulation of bladder cancer cells by phospholipase C-ε through EXO1, the authors noted that gene expression of EXO1 was significantly higher in 72 bladder cancer tissue specimens than in 24 adjacent paracancerous tissue samples." (PMID 33912448, 2021).
cervical adenocarcinoma (1 paper, 2025). An adenocarcinoma arising from the cervical epithelium. "To this end, we generated constitutive knockout (KO) cell lines for EXO1 in diploid chronic myelogenous leukaemia eHAP and in cervical adenocarcinoma HeLa Kyoto cells harbouring an integrated inducible Cas9." (PMID 41006228, 2025).
colorectal adenoma (1 paper, 2016). An adenoma that arises from the colon or rectum. "In support of this, a potential link between Exo1 polymorphisms and premalignant lesions (colorectal adenoma) in tobacco smokers has been reported." (PMID 27004475, 2016).
colorectal tumors (1 paper, 2024). "Analysis of TCGA data also revealed significantly increased EXO1 expression in colorectal tumors." (PMID 38840170, 2024).
cystic fibrosis (1 paper, 2025). Autosomal recessive disorder caused by pathogenic variants in the CFTR gene (cystic fibrosis transmembrane conductance regulator), which encodes a chloride and bicarbonate channel expressed in epithelial cells, and follow the diagnosis criteria. "Specifically, we fused FEN1, EXO1, and a truncated EXO1 variant (HEX-N2 domain) to the PEmax using either 16-amino acid or 4-amino acid linkers as part of our therapeutic development strategy for cystic fibrosis treatment." (PMID 40869263, 2025).
female infertility (1 paper, 2024). Diminished or absent ability of a female to achieve conception. "This first variant of EXO1 found in DOR confirms the involvement of EXO1 in female infertility in humans and in the maintenance of the OR." (PMID 39595984, 2024).
fibrosarcoma (1 paper, 2019). A malignant mesenchymal fibroblastic neoplasm affecting the soft tissue and bone. "In parallel with decreased telomerase activities, TPX2 or EXO1 knockdown reduced the viability of fibrosarcoma HTC75 cells and HepG2 cells." (PMID 31179925, 2019).
kidney injury (1 paper, 2024). Trauma to the kidney. "In contrast, EXO1 had minimal effects on renal function and the severity of AKI, suggesting that Mφ-derived exosomes from Atg7Δmye mice exacerbated kidney injury." (PMID 38782909, 2024).
lymph node metastasis (1 paper, 2020). "Patients with a high expression level of EXO1 showed poor prognosis and a high risk of lymph node metastasis." (PMID 33193734, 2020).
lymphocytic thyroiditis (1 paper, 2025). "In patients with THCA, the expression levels of EXO1 were higher in those with a history of lymphocytic thyroiditis in the thyroid gland disorder than in patients with nodular hyperplasia." (PMID 40433389, 2025).
mismatch repair deficiency (1 paper, 2016).
multiple myeloma (1 paper, 2021). "Another study showed that ILF2/YB‐1/U2AF2 complex promotes DDR‐related mRNA processing that affects the expression of FANCD2 and EXO1 in multiple myeloma." (PMID 34709752, 2021).
Pythiosis (1 paper, 2020). A granulomatous disease caused by the aquatic organism PYTHIUM insidiosum and occurring primarily in horses, cattle, dogs, cats, fishes, and rarely in humans. "The recombinant Exo1 protein, when available, could facilitate its functional study, and also serve as a candidate for the development of a novel diagnostic or therapeutic modality for pythiosis." (PMID 32596527, 2020). "The immunoreactivity of Exo1 was also evaluated by Western blot and the serum samples with lowest-, medium-, and highest-level ELISA values from the pythiosis patients (P4, P3, and P10, respectively) and the controls (N7, N2, and N8, respectively)." (PMID 32596527, 2020). "The unrecognition and cross-reactivity of Exo1 by some pythiosis and control sera suggested that the E. coli-derived Exo1 was not a suitable candidate for the development of a diagnostic test." (PMID 32596527, 2020). "Regarding the immunological property, Exo1 of P. insidiosum was reactive against the pythiosis sera tested, and the average ELISA value of the sera from the pythiosis patients was significantly higher than that from the control individuals." (PMID 32596527, 2020). "The immunoreactivity of the recombinant Exo1 was assessed by ELISA and 24 serum samples from pythiosis patients (P1-12) and healthy blood donors (controls; N1-12)." (PMID 32596527, 2020). "ELISA and Western blot analyses demonstrated the immunoreactivity of Exo1 against pythiosis sera." (PMID 32596527, 2020). "The serum P4 might be derived from a pythiosis patient infected with a P. insidiosum strain that minimally expressed Exo1 and resulted in an undetected antibody response." (PMID 32596527, 2020). "However, based on the Western blot assay, Exo1 was unrecognized by the pythiosis serum P4 (which had a relatively-low ELISA value) while recognized by the control serum N8 (which had a relatively-high ELISA value)." (PMID 32596527, 2020). "Taken into account its conserve and immunoreactive feature across various P. insidiosum strains, the recombinant Exo1 could serve as an extra protein to enhance the effectiveness of the current form of the crude extract-derived vaccine against pythiosis." (PMID 32596527, 2020). "The recombinant Exo1 can be produced at an unlimited amount and could serve as an extra protein to enhance the effectiveness of the current form of the vaccine against pythiosis." (PMID 32596527, 2020). "The soluble recombinant Exo1 protein was successfully generated and purified, and it could serve as a candidate for downstream applications, such as the development of an effective vaccine against pythiosis." (PMID 32596527, 2020).
skin cancer (1 paper, 2022). "In skin cancer, PAXIP1, EXO1, and RIF1 associated with dHRVAE1, the component correlating with SNV signature 3 mutations." (PMID 35764656, 2022).
squamous cell carcinoma (1 paper, 2025). A carcinoma arising from squamous epithelial cells. "However, in specific subgroups, such as the basal type of PAM50 classification in BRCA, T2 stage or squamous cell carcinoma in CESC, and FIGO stage IV in OV, higher EXO1 expression was associated with better OS." (PMID 40433389, 2025). "However, for BRCA patients with basal type of PAM50 classification, CESC patients with T2 stage, squamous cell carcinoma of histological type, and OV patients with FIGO stage IV, high EXO1 expression was associated with better OS." (PMID 40433389, 2025).
Stroke (1 paper, 2020). Sudden impairment of blood flow to a part of the brain due to occlusion or rupture of an artery to the brain. "At 28 days after stroke, the EXO1 group score was 5.25 ± 0.4523, which was significantly lower than that of the pMCAO group, approximately 6.583 ± 0.5149 (P < 0.001)." (PMID 33013286, 2020).
thyroid gland disorder (1 paper, 2025). A disease involving the thyroid gland. "In THCA, EXO1 expression was associated with age, histological type, and a history of thyroid gland disorder." (PMID 40433389, 2025).
type 1 diabetes (1 paper, 2021). "The two most enriched gene sets in type 1 diabetes for all exocrine regions (ie, Exo1, Exo2, and Exo3, respectively) were myc targets v2 and estrogen response early, although the later was not significantly enriched in Exo2." (PMID 34031141, 2021). "Most of these were found in Exo1, in which 19 genes were downregulated and four upregulated in type 1 diabetes." (PMID 34031141, 2021).
uterine sarcoma (1 paper, 2025). "Genetic mutation analysis indicates a higher frequency of EXO1 gene mutations in uterine sarcoma and BRCA." (PMID 40433389, 2025).
viral infection (1 paper, 2020). "This category contained the nucleases RNASE7, RNASEH2A, RNASE10, and EXO1, as well as proteins regulating nucleases, like the OAS-protein family that are known to activate RNase L activity upon viral infection." (PMID 32545414, 2020).
cancer (83 papers, 2005 to 2026). A tumor composed of atypical neoplastic, often pleomorphic cells that invade other tissues. "Results of this screen resulted in seven distinct chemicalscaffolds with EXO1-selective inhibitory activity that synergizedwith the BRCA1-deficiency in human cancer cells." (PMID 40378357, 2025). "We next examined EXO1 synthetic lethal interactions with genome stability maintenance factors with frequent loss-of-function mutations or deletions in cancers." (PMID 41006228, 2025). "Previous reports have suggested that mutations in the EXO1 gene can lead to protein dysfunction and increased susceptibility to certain cancers." (PMID 40433389, 2025). "Specifically, we uncover cancer vulnerabilities amongst synthetic lethal hits with EXO1 loss, including deficiencies in BRCA1-A complex factors, FA pathway genes and the splicing factor and tumour suppressor ZRSR2." (PMID 41006228, 2025). "To further explore the association between EXO1 and cancer immunity, we investigated the relationship between EXO1 expression and different immune subtypes using the TISIDB database." (PMID 40433389, 2025). "After confirming the presence of EXO1 alterations, we investigated the association between mRNA expression of EXO1 and its methylation status in selected cancers." (PMID 40433389, 2025). "While its association with cancer has been widely explored, its mechanisms are relatively complex and less directly connected to DNA repair compared to EXO1." (PMID 39777332, 2024). "Several studies have shown a strong association between EXO1 and the prognosis of malignant tumors, including PCa." (PMID 38279172, 2024). "Based on previous studies suggesting that the EXO1 nuclease is also implicated in reversed fork degradation in BRCA1-deficient cancer cells, we tested the effect of EXO1 knockdown in BRCA1-depleted U2OS cells." (PMID 38943334, 2024). "Currently, genetic polymorphisms in DNA repair are an important factor affecting different cancer, nevertheless association between EXO1, RAP1, PMS1, and PMS2." (PMID 36277983, 2022). "Genome‐level studies have identified specific mutations in the EXO1 gene as risk alleles for different types of cancers." (PMID 35757968, 2022). "Several experimental and bioinformatic studies have shown the importance of EXO1 in replication, DNA repair pathways, cell cycle checkpoints, and its association to cancer." (PMID 35757968, 2022). "Owing to its role in DNA repair, maintenance of chromatin stability, and modulation of DNA recombination, the relationship between polymorphisms of EXO1 and the risk of cancer had been well studied, with at least nine genetic variants identified." (PMID 35444699, 2022). "Mutations in specific locations in EXO1 have been reported to inactivate proteins that increase cancer susceptibility." (PMID 34567091, 2021). "EXO1 has been associated with different types of cancers, including Lynch Syndrome, breast, ovarian, lung, pancreatic, and gastric tract cancer." (PMID 30585186, 2018). "By contrast, the FANCC and EXO1 knockouts are more similar to HR-deficient cancers; defined by general genomic instability and an excess of deletions with microhomology at the breakpoint junction." (PMID 29717121, 2018). "To date, only a few molecular epidemiological studies have investigated other EXO1 polymorphisms and cancer susceptibility in various populations, such as A-1419G (rs3754093), G670E (rs1776148), C498T (rs1635517), and L757P (rs9350)." (PMID 27387683, 2016). "After reading the title or abstract, 41 studies concerning the associations of the nine EXO1 polymorphisms and cancer susceptibility were selected for further consideration." (PMID 27387683, 2016).
cancer (continued). "Recently, the associations between EXO1 genetic polymorphisms and susceptibility to various type of cancers had been widely investigated." (PMID 27387683, 2016). "In the present meta-analysis, we had widely reviewed all eligible publications that were based on case-control data to derive a more precise and up-to-date estimation of associations between polymorphisms in EXO1 and cancer susceptibility." (PMID 27387683, 2016). "Owing to the importance of EXO1 polymorphisms, an increasing number of studies have explored the associations of EXO1 polymorphisms and cancer risk." (PMID 27387683, 2016). "We carried out a meta-analysis of 7 case-control studies to clarify the association between the Exo1 K589E polymorphism and cancer risk." (PMID 24810280, 2014). "The conclusions of the Exo1 polymorphisms on cancer susceptibility studies remain inconsistent, which is partially attributed to the heterogeneity of the cancer subtype, small sample size, and ethnicity of the patients." (PMID 24810280, 2014). "In the present study, we were first analyzed the association of Exo1 K589E of cancer from 7 studies." (PMID 24810280, 2014). "Then in order to obtain the exact consequence of the relationship between Exo1 K589E polymorphism and cancer susceptibility, stratified analyses by ethnicity and smoking status were performed." (PMID 24810280, 2014). "Further stratification analysis by ethnicity, the results showed that Exo1 K589E polymorphism was significantly linked to cancer risk." (PMID 24810280, 2014). "In summary, this meta-analysis suggested that the Exo1 K589E polymorphism was significantly associated with increased risk of cancer, especially in smokers." (PMID 24810280, 2014). "In the present study, we have extensively reviewed literature and performed a meta-analysis based on all eligible case-control published data to evaluate the association between Exo1 K589E polymorphisms and cancer susceptibility." (PMID 24810280, 2014). "The pooled results revealed that Exo1 K589E Lys allele was associated with an increased risk for developing cancer." (PMID 24810280, 2014). "Based on these observations, we sought to test the hypothesis that EXO1 participates in compensatory pathways that DDR-deficient cancer cells critically rely on for viability." (PMID 41006228, 2025). "Aberrant function or overactivation of exonuclease 1 (EXO1) may be associated with cancer tumor development, drug resistance, and response to immunotherapy in female-related cancers." (PMID 40433389, 2025). "In these cancers, elevated EXO1 expression is associated with poor survival outcomes." (PMID 41323735, 2025). "In conclusion, this study reveals extensive synthetic lethal genetic interactions with EXO1 in human cells, which defines a framework for EXO1-based targeting of cancers with deficiencies in DDR pathways for which current therapeutic approaches are not sufficiently effective." (PMID 41006228, 2025). "Based on the correlation strength, we identified the top 100 genes significantly associated with EXO1 in each of the six cancer types and determined their intersection, yielding 15 genes that exhibited consistent high correlation with EXO1 across all six cancers." (PMID 40433389, 2025). "Exo1 meets all criteria in such an important DNA replication-coupled excision repair pathway as its deficiency diversifies the neoantigen and benefits the immunotherapy cancer patients." (PMID 38714348, 2024). "EXO1 polymorphisms have been reported to be associated with cancer susceptibility." (PMID 36277983, 2022). "The deficiency of EXO1 activity induced by germline mutation can lead to the inactivation of DNA mismatch repair pathway, hypermutation in genome and further predispose the carriers to develop cancer." (PMID 36255267, 2022). "Among them, BUB1 and EXO1 were associated with patient survival of all three cancers of interest." (PMID 35757968, 2022).